HGF (hepatocyte growth factor)
Diseases named in the same sentence as HGF in open-access papers (continued):
Sharing a sentence is not in itself a finding about the gene and the disease.
peripheral arterial disease (8 papers, 2007 to 2025). A disorder of the arteries supplying the upper and lower extremity and the visceral organs. "pDNA encoding human hepatocyte growth factor (HGF) has shown significant activity in clinical trials for the treatment of peripheral arterial disease, and was first approved in Japan in 2019 for use by intramuscular injection." (PMID 40871075, 2025). "Recently, in 2019, plasmid DNA (pDNA) encoding the human hepatocyte growth factor (HGF) gene was first approved for peripheral arterial disease in Japan." (PMID 33430003, 2021). "This concept is supported by recent reports that HGF treatment produced therapeutic benefit against peripheral arterial disease." (PMID 25047123, 2014). "Phase-III trial of HGF gene therapy for peripheral arterial diseases told us the answer for that." (PMID 23675038, 2007). "Twenty-two patients with peripheral arterial disease or Buerger's disease staged as Fontaine IIb (n = 7), III (n = 4), or IV (n = 11) were treated with two injections of either 2 mg or 4 mg of HGF plasmid." (PMID 24294599, 2013). "In the pilot clinical study, similar improvements were seen in gene therapy using HGF in peripheral arterial diseases which might be more noninvasive." (PMID 23675038, 2007). "Furthermore, we have confirmed that intra-arterial administration of recombinant HGF induced angiogenesis in a rabbit hindlimb ischemia model and examined the feasibility of gene therapy using HGF to treat peripheral arterial disease rather than recombinant therapy, because of its disadvantages." (PMID 23675038, 2007).
Pleural effusion (8 papers, 1996 to 2025). The presence of an excessive amount of fluid in the pleural cavity. "Meanwhile, highly sensitive enzyme-linked immunosorbent assay techniques can quantitatively measure HGF concentrations in liquid samples such as blood or pleural effusion to aid in diagnosis." (PMID 40136462, 2025). "Pleural effusion Galectin-1, NRG1-β1, Osteopontin, Mesothelin, shed SDC-1, VEGF and TIMP-1 levels are more reliable diagnostic biomarkers than HGF and MMP in pleural effusion." (PMID 32731396, 2020). "In addition to this, we showed that SDC-1 and HGF had higher concentrations in exosomes derived from pleural effusion from metastatic adenocarcinoma patients." (PMID 34827604, 2021). "In order to determine the prognostic value of pleural effusion derived Angiopoietin-1, HGF, MMP-7, Osteopontin, TIMP-1, Galectin, Mesothelin, NRG1-b1, SDC-1 and VEGF, we divided patients in two groups depending on the established cut-off value for all analytes." (PMID 32731396, 2020). "The concentration of HGF secreted by patient-derived bone marrow stem cells over 48 hr was reported to be 2–12 ng/mL and the concentration of HGF was reported to be 0.5–11 ng/mL in pleural effusions from cancer patients." (PMID 29550255, 2018). "We quantified the expression of HGF, adenosine deaminase (ADA), and interferon gamma (IFN-γ) in pleural effusion (PE) in 97 TPE subjects and 116 non-TPE subjects using an enzyme-linked immunosorbent assay (ELISA) or a fully automatic biochemical analyzer." (PMID 37485530, 2023).
preeclampsia (8 papers, 2014 to 2025). Preeclampsia is a hypertensive disorder of pregnancy that is characterized by new-onset hypertension with proteinuria presenting after 20 weeks of gestation, and depending on mild or severe forms may initially present with severe headache, visual disturbances, and hyperreflexia. "We found that the growth regulated oncogene A (GROA) and interleukin-9 (IL-9) were associated with the development of pregnancy hypertension, whereas interleukin-10 (IL-10) and hepatocyte growth factor (HGF) were linked to the occurrence of preeclampsia." (PMID 38362587, 2023). "There are studies describing HGF to inhibit apoptosis in the placentas of pathological pregnancies, for example, in the case of preeclampsia." (PMID 34401645, 2021). "Further specific research is needed to determine whether the increase in EGF, HGF, LIF and SCF is a consequence of preeclampsia or if it indicates changes in factors associated with preeclampsia." (PMID 41006365, 2025). "This study aimed at a comparative evaluation of pro-inflammatory (TNFα) and anti-inflammatory (CD206, MMP9, HGF) markers, as well as the levels of estrogen receptor α, expressed by decidual macrophages in normal pregnancy and in patients with early- and late-onset preeclampsia." (PMID 33672970, 2021). "No significant findings have been detected, except from a trend toward higher placental CD68+ cells (P = 0.07) and HGF (P = 0.06) in preterm placentas and to higher CCL5 in patients with preeclampsia (P = 0.07)." (PMID 33313931, 2021). "EGF, HGF and LIF and SCF levels were significantly elevated in preeclampsia." (PMID 41006365, 2025). "In conclusion, we confirmed an increase in EGF, HGF, LIF and SCF in preeclampsia." (PMID 41006365, 2025). "The observed downregulation of estrogen receptor α, HGF and CD206 may contribute to the balance of pro- and anti-inflammatory macrophages and thereby to pathogenesis of preeclampsia." (PMID 33672970, 2021). "Furthermore, significantly decreased levels of HGF and CD206 were observed in both preeclampsia groups compared with the control group." (PMID 33672970, 2021).
stomach cancer (8 papers, 2009 to 2024). "Catenacci and colleagues reported a case of complete response in a patient with advanced gastric tumor and MET gene polysomy between four and six copies, but it was associated with a high serum HGF level." (PMID 28960893, 2017). "It remains to be seen if HGF expression with gastric tumors can be reliably measured and if it proves to be a clinically useful biomarker to select patients for anti-MET therapy." (PMID 24930887, 2014). "In preclinical models, MET gene amplification results in constitutive activation of the MET receptor and an oncogenic addiction to the MET signaling pathway thereby rendering gastric tumor cells acutely sensitive to HGF/MET axis inhibition." (PMID 24930887, 2014). "c-MET (pY1003) phosphorylation was detected in only two gastric tumor lysates (G2, G3) and these same tumors were also positive for HGF/c-MET complexes by proximity FFPE assay." (PMID 21283737, 2011). "We also compared our HGF/c-MET measurements in the proximity FFPE assay with the levels of c-MET (pY1003), c-MET (pY1234/1235), and c-MET (pY1349) phosphorylation detected in NSCLC and gastric tumors." (PMID 21283737, 2011).
Arthritis (7 papers, 2014 to 2026). Inflammation of a joint. "In vivo, inhibition of the HGF-c-Met pathway with savolitinib significantly suppressed arthritis development and reduced synovial inflammation." (PMID 41694341, 2026). "MSCs expressing hepatocyte growth factor (HGF) alleviated arthritis symptoms in CIA mice, but in the late stages of disease, the effect was no better than treatment with MSCs alone." (PMID 37038221, 2023). "However, after day 41, both the arthritis score and incidence of the DPSCs-HGF treatment group soared intensively, while those of the DPSCs-Null treatment group began to decrease." (PMID 32522231, 2020). "We previously reported that the HGF antagonist, NK4, inhibited arthritis and bone destruction by inhibiting angiogenesis and inflammatory cell infiltration in the synovium in SKG mice." (PMID 25941631, 2015). "We previously demonstrated that the HGF antagonist, NK4, inhibits arthritis by suppressing angiogenesis and inflammatory cytokine production by CD4+ T cells in SKG mice, an animal model of RA." (PMID 25941631, 2015). "We previously demonstrated that blocking c-Met signaling using a HGF antagonist, NK4, inhibited arthritis in a RA model of SKG mice." (PMID 25332857, 2014). "We previously reported that blocking c-Met signaling using HGF antagonisit, NK4, inhibited arthritis in RA model of SKG mice." (PMID 25332857, 2014).
B-cell lymphoma (7 papers, 2012 to 2024). "HGF increased the adhesion of c-MET-positive B cell lymphoma cells to fibronectin and collagen, mediated via β1-integrin, and furthermore, promoted migration and invasion." (PMID 27923392, 2016). "With the recent development of clinical-grade agents targeting the HGF/MET pathway, inhibition of this pathway is currently considered a rational and promising strategy for the treatment of patients with B-cell lymphoma and MM." (PMID 23379953, 2013). "The HGF/MET pathway is an emerging target for the treatment of MM, B-cell lymphomas and solid tumors." (PMID 23232072, 2012). "In this respect, HGF released by both MM cells and BMSC is rapidly emerging as a potential target for treatment both in MM and in B-cell lymphomas." (PMID 23232072, 2012).
dengue (7 papers, 2013 to 2025). "Meta‐analyses have similarly shown that the initial acute inflammatory response with hepatic involvement is a key determinant of disease progression in dengue, suggesting the promising value of HGF for dengue severity prediction." (PMID 40704559, 2025). "PLTs were also observed to negatively correlated with HGF (ρ = –0.4, p < 0.001) and SCGF‐beta (ρ = –0.5, p < 0.001), suggesting the potential associations of HGF and SCGF‐beta with dengue." (PMID 40704559, 2025). "In contrast, levels of IL-6, IL-8, HGF and G-CSF were significantly increased in severe dengue compared to uncomplicated disease." (PMID 23717702, 2013). "HGF is another growth factor involved in dengue pathogenesis." (PMID 36297236, 2022). "This study demonstrates that among other biomarkers, TNF‐beta, HGF, MIP‐1 beta, and SCGF‐beta are strongly associated with dengue, and together with duration of symptoms before hospital admission, these markers could help identify cases requiring hospitalization on admission." (PMID 40704559, 2025). "Six studies analyzed HGF, and four found increased levels in dengue patients, most of them severe dengue compared with nonsevere dengue and/or healthy controls, including one study in children only." (PMID 36297236, 2022). "Thus, increased levels of VEGF, GM-CSF, G-CSF, TGF-β, and HGF, as well as decreased levels of PDGF and EGF, were observed in severe dengue in most studies." (PMID 36297236, 2022). "The HGF receptor (HGFR) has been implied as a co-receptor for adeno-associated virus type 2 infections, and although this has not been shown for dengue virus entry, the HGF per se has been found to be increased in the serum of dengue infected patients." (PMID 23889893, 2013).
diabetic nephropathy (7 papers, 2012 to 2023). "ONO-1301, a novel nonprostanoid IP agonist, was used in models of type 1 diabetic nephropathy and UUO, and showed a therapeutic effect on treating diabetic nephropathy via inducing hepatocyte growth factor (HGF) to counteract TGF-β." (PMID 29899878, 2018). "We previously demonstrated hepatocyte growth factor (HGF) gene therapy was able to induce regression of glomerulosclerosis in diabetic nephropathy through local reparative mechanisms." (PMID 22460762, 2012). "We have previously studied the effect of HGF gene therapy on diabetic kidney disease in rats and have demonstrated HGF-supplementation-induced regression of glomerular sclerosis." (PMID 22460762, 2012). "Altogether, our findings provide new evidence about the therapeutic role of HGF and open new opportunities for inducing renal regeneration in diabetic nephropathy." (PMID 22460762, 2012). "We were also able to reproduce previous findings from our group concerning the functional and histological benefits of HGF gene therapy on diabetic nephropathy in this model." (PMID 22460762, 2012). "In order to study whether bone-marrow-derived cells are involved in the reparative mechanisms of HGF on diabetic kidney disease, we have created chimeric diabetic db/db mice." (PMID 22460762, 2012). "Therefore, the role of HGF in the pathogenesis of diabetic kidney diseases needs further research." (PMID 36836700, 2023). "Hepatocyte growth factor regulates the PI3K/Akt-GSK3 sh-TFEB axis and protects diabetic nephropathy through the podocyte autophagy-lysosome pathway." (PMID 36707848, 2023). "HGF can bind to MET, which is a transmembrane receptor of the tyrosine kinase superfamily, and its inhibitory effects on tissue fibrosis have been confirmed in various research models, such as residual kidney, unilateral ureteral obstruction, and diabetic nephropathy." (PMID 31781634, 2019).
inflammatory bowel disease (7 papers, 2015 to 2025). A spectrum of small and large bowel inflammatory diseases of unknown etiology. "Although HGF is firstly noted in a mitogenic protein in the hepatocyte of rats, it’s subsequently used in the mucosal repair during inflammatory bowel disease." (PMID 31920638, 2019). "The recombinant HGF protein exerts a therapeutic effect on several animal models of inflammatory bowel disease (IBD) by modulating intestinal epithelial cell proliferation, migration and inflammation." (PMID 25933295, 2015). "The assessment of circulating transforming growth factor-β (TGF-β) and hepatocyte growth factor (HGF) levels could be a good biologic acute phase response marker of inflammatory bowel disease activity." (PMID 32377513, 2020). "In addition, several studies have shown that HGF can suppress common proinflammatory pathways and reduce acute and chronic inflammation in various diseases (e.g., inflammatory bowel disease [IBD], airway inflammation, and glomerulonephritis)." (PMID 40129451, 2025).
metastatic colorectal cancer (7 papers, 2014 to 2023). "Similar to the result of the present study, high levels of serum HGF was associated with poor prognosis in KRAS wild-type patients with metastatic colorectal cancer." (PMID 26716644, 2016). "The strikingly different efficacy of AIs in WT and hHGF KI SCID mice suggests that stroma-derived HGF represents a major source of resistance to anti-angiogenic therapy of metastatic colorectal cancer, at least in the orthotopic models analyzed." (PMID 28445144, 2017). "In 2015 Takahashi and colleagues found a correlation between serum levels of HGF and occurrence of EGFRI-induced skin toxicity in metastatic colorectal cancer (inverse correlation)." (PMID 28456787, 2017). "They analyzed serum levels of different growth factors in patients with metastatic colorectal cancer who were treated with an anti-EGFR antibody and also found a significant inverse correlation between serum levels of HGF and OS." (PMID 28456787, 2017). "CAFs are known to secrete many different growth factors, cytokines, and chemokines, including hepatocyte growth factor (HGF), which activates the MET receptors to protect the CSCs from apoptosis in response to the cetuximab monotherapy targeting the EGFR in metastatic colorectal cancer." (PMID 29681949, 2018). "Several clinical trials using inhibitors of HGF/Met, MAP-kinase, m-TOR pathways and Wnt-signaling or small-molecule beta catenin inhibitors are ongoing in metastatic colorectal cancer, and optimal patient selection for effective use of these antagonists remains to be established." (PMID 25083765, 2014).
metastatic melanoma (7 papers, 2019 to 2024). A melanoma that has spread from its primary site to another anatomic site. "A recent study showed that low level of circulating HGF correlated to superior response to anti-PD-1 therapy in patients with metastatic melanoma." (PMID 38776028, 2024). "HGF directly inhibited the cytolytic function of c-Met+ CTLs, both in 2D in vitro assays and in vivo, leading to reduced T cell responses against metastatic melanoma." (PMID 38137344, 2023). "Although a fraction of MBM exhibits immune cell subset enrichment and interferon response signatures and responds to ICi therapy, MET-expressing brain metastatic melanoma cells may benefit from HGF released by stromal cells to drive progression." (PMID 38386085, 2024). "MET receptor phosphorylation/activation maybe elicited by inflammatory processes in brain metastatic melanoma cells via stroma cell-released HGF." (PMID 38386085, 2024). "Interestingly, HGF concentration in serum was found to be higher in the later stages of metastatic melanoma." (PMID 33233528, 2020). "In contrast, in a study looking at HGF serum levels ahead of nivolumab or pembrolizumab treatment of patients suffering from metastatic melanoma, non-responders showed significantly higher serum levels than responders." (PMID 33233528, 2020). "Negative association between serum HGF and ORR has been previously observed in 29 Japanese patients with metastatic melanoma receiving either nivolumab or pembrolizumab, and the present study confirms the validity of this association in a larger sample of European ancestry." (PMID 36007304, 2022).
osteoarthritis (7 papers, 2014 to 2024). A noninflammatory degenerative joint disease occurring chiefly in older persons, characterized by degeneration of the articular cartilage, hypertrophy of bone at the margins and changes in the synovial membrane. "Changes in HGF/c-Met have also been linked to pathophysiological changes in degenerative joint diseases, such as osteoarthritis (OA) and intervertebral disc degeneration (IDD)." (PMID 33218127, 2020). "Osteoarthritis osteoblasts produce the hepatocyte growth factor (HGF) which plays a key role in cartilage loss." (PMID 28425564, 2017). "HGF and c-Met expression in RA synovium was increased compared to osteoarthritis synovium suggesting increased c-Met signaling in RA synovial cells." (PMID 25332857, 2014). "In this article, we provide an overview of the potential role of HGF for the treatment of degenerative joint disease and discuss the HGF/c-Met system, anticipated to be of value for identifying causes and therapies for degenerative disorders of the synovial joint and spine." (PMID 33218127, 2020). "However, there are many studies on the relationship between HGF and osteoarthritis, and the results are controversial or even contradictory." (PMID 32571421, 2020).
Parkinson disease (7 papers, 2011 to 2022). A progressive degenerative disorder of the central nervous system characterized by loss of dopamine producing neurons in the substantia nigra and the presence of Lewy bodies in the substantia nigra and locus coeruleus. "It was shown that the culture supernatant of HGF/UC‐MSCs could promote neural regeneration, reduce intracellular free calcium levels and promote the intracellular levels of bound calcium in a Parkinson's disease cell model." (PMID 35922965, 2022). "A group in Japan injected plasmid carrying HGF gene into PD rat model and found significant reduction of symptoms, suggesting that overexpression of HGF can prevent death of dopaminergic neurons in Parkinson rats." (PMID 25276829, 2014). "We conclude by presenting support for the notion that angiotensin agonists may be useful in activating the HGF/c-Met receptor system in order to provide cerebroprotection and encourage synaptogenesis in Parkinson's disease patients." (PMID 23213621, 2012). "Salehi and Rajaei reported that HGF could be involved in the pathogenesis of Parkinson's disease." (PMID 25276829, 2014). "Insignificant increase in HGF and a marked increase in FGF-7 expression were also observed in our study, suggesting that E. umbellata extracts could potentially be used in the treatment of disorders with neuro-inflammation, such as Alzheimer’s or Parkinson’s diseases." (PMID 33552740, 2021). "However, HGF was also shown to influence several non-tumorous pathways, including those involved in Parkinson's and Huntington's disease, implying that HGF may have a role in nervous system diseases." (PMID 26099202, 2015).